Y_RNA (Y RNA )
Gene: Miscellaneous RNA gene on chromosome 14 (22,867,818 to 22,867,917, forward strand). Ensembl gene ENSG00000199716.
Homologues: Orthologues: chimpanzee Y_RNA (100% identical), macaque Y_RNA (94% identical). Paralogues in human: Y_RNA (89% identical), RNY3 (88% identical), Y_RNA (88% identical), RNY3P1 (87% identical), Y_RNA (87% identical), Y_RNA (86% identical), Y_RNA (85% identical), RNY3P14 (84% identical), Y_RNA (84% identical), RNY3P9 (83% identical), Y_RNA (83% identical), RNY3P11 (82% identical), and 95 more.